F2R (coagulation factor II thrombin receptor)
Diseases named in the same sentence as F2R in open-access papers (continued):
Sharing a sentence is not in itself a finding about the gene and the disease.
cancer (49 papers, 2005 to 2025). A tumor composed of atypical neoplastic, often pleomorphic cells that invade other tissues. "Surprisingly, we have also observed differential expression of the F2R gene (encoding coagulation factor II thrombin receptor), which, according to the literature, can stimulate the migration and invasion of cancer cells under SOX9 influence." (PMID 35216085, 2022). "Coagulation factor 2 thrombin receptor (F2R), a key component in the thrombosis process, has been demonstrated up-regulated in various cancers and was associated with several protumoral responses, including primary growth, invasion, metastasis, and angiogenesis." (PMID 36245971, 2022). "These cell line models show high F2R gene/protein expression and therefore provide a suitable platform to investigate F2R-mediated cancer mechanisms." (PMID 40943451, 2025). "Studies show that F2R can influence platelet mobilization as well as epidermal growth factor receptor signaling pathways to promote cancer progression." (PMID 35186111, 2022). "F2R may also be involved in prevention of apoptosis, morphogenesis of photoreceptors and survival of cancer cells through a Bcl-xL-dependent mechanism." (PMID 35410372, 2022). "Finally, module 4 included the genes PLCB4, MMP1, CTNNB1, EGF, F2R, and LPAR4, associated with pathways in cancer, Rap1 signalling pathway, and phospholipase D signalling pathways." (PMID 31178673, 2019). "In addition to the regulation of clot formation, the protease thrombin can also have a direct effect on cancer cells and the cells of the tumor microenvironment (TME) through its ability to interact with the protease-activated receptor-1 (PAR-1), a G-protein coupled receptor encoded by the gene F2R." (PMID 35053621, 2022). "F2R, also known as protease-activated receptor 1 (PAR1), is a G-protein-coupled receptor that plays a critical role in coagulation, inflammation, and cancer progression, including the migration, invasion, and proliferation of cancer cells." (PMID 41515956, 2025). "Additionally, public data from GSE172016 demonstrated significantly high F2R expression in paclitaxel-resistant OVCAR3 and TOV21G cells, further supporting the role of F2R in sensitizing cancer cells to chemotherapy treatments." (PMID 40943451, 2025). "In addition, several genes that were reported to be related to a less cancer aggressiveness or metastatic potential were found to be increased upon PAGE4 overexpression, including ACTA2, FBLN1 and F2R." (PMID 30658679, 2019).
tumor (48 papers, 1998 to 2026). "GSEA identified the signaling pathway associated with F2R mRNA expression in GC, revealing a significant association with tumor progression." (PMID 38291086, 2024). "Whilst protein expression depends on mRNA transcription, there is often not a direct correlation between gene and protein expression, hence the need to investigate F2R protein expression in patient-derived tumor samples." (PMID 40943451, 2025). "High F2R expression activates tumor-related immune cells, leading to potentially improved outcomes for patients with BC." (PMID 39655193, 2024). "In the present study, cluster mCAF1/2 received immune signals from suppressive T cells (CD8+ exthausted T cells and Treg) through GZMA and its receptor F2R instead, as a potential mediator of tumour microenvironment." (PMID 36855810, 2023). "Conversely, tumor-associated macrophages (TAM) expressed high levels of PLAU and PLAUR, and tumor-associated endothelial cells expressed high levels of PLAT, F2R and SERPINE1." (PMID 35053621, 2022). "PAR-1/F2R, a plasma membrane receptor that mediates thrombin-dependent angiogenesis, is often found expressed in tumor cells and has been shown to protect hypoxic cells from cell death." (PMID 24489651, 2014). "Comprehensive immune profiling showed that high expression of F2R/MXRA5 was associated with an immunosuppressive microenvironment, exhibiting reduced infiltration of dendritic cells and macrophages, elevated TIDE scores, and decreased tumor purity." (PMID 41968212, 2026). "Furthermore, delving into the role of F2R within the tumor microenvironment (TME), including its interactions with immune cells and immune checkpoints, unveils opportunities for immunomodulatory strategies." (PMID 38291086, 2024). "Targeting F2R could potentially reshape tumor-immune dynamics, thereby enhancing the efficacy of immunotherapy in BC." (PMID 39655193, 2024). "Targeting F2R could potentially reshape the dynamics between tumor and immune system, thereby improving the efficacy of immunotherapy for STAD." (PMID 38291086, 2024). "Additionally, F2R protein expression was examined in both healthy and BC tumor tissues using IHC data." (PMID 39655193, 2024). "F2R activation may facilitate platelet activation, tumor cell proliferation, apoptosis, and angiogenesis." (PMID 35836573, 2022). "Moreover, the low expression of GZMA and F2R was positively correlated with PD-1 and PD-L1, impaired tumor suppression by PD-1 mAb, and also predicted aggressive clinicopathological characteristics and a poor prognosis." (PMID 35256589, 2022). "Tumor-bearing scaffolds had lower expression of interferon γ (Ifng) and killer cell lectin like receptor G1 (Klrg1), markers of T-cell activation/effector T cells, and, conversely, up-regulation of coagulation factor II thrombin receptor (F2r), a marker of exhausted T cells." (PMID 33782087, 2021). "The senescence-like fibroblasts also highly expressed F2R and CD24, implying a role in suppressing anti-tumor immunity." (PMID 36198671, 2022). "Unfortunately, two tumor cells exhibited negative expression of F2R in tumor tissues." (PMID 35256589, 2022). "Four GPCRs were also over-expressed to a significant level within all three (WNT, SHH, Non-WNT/SHH) categorized tumor groups (FZD2, RPLP0, EDG4 and F2R)." (PMID 24252460, 2013).
infection (7 papers, 2011 to 2025). The state of being infected such as from the introduction of a foreign agent such as serum, vaccine, antigenic substance or organism. "Upregulated genes in both infection and inflammation pathways were F2R, which links coagulation with inflammation; ADAR, crucial in antiviral immune responses; and FCAR, involved in IgA responses at mucosal sites." (PMID 41416938, 2025).
kidney disease (2 papers, 2023 to 2025). "The findings of this study indicate that NGR1 has the potential to mitigate kidney disease and exert regulatory effects on VEGFA, F2R, and FGF1." (PMID 37415174, 2023).
myopathy (1 paper, 2015). A disease of the muscle in which the muscle fibers do not function properly. "Birds suffering from this myopathy exhibit down-regulation of eight hemostatic genes (A2M, FGA, FGB, FGG, KNG1, SERPINC1 and VWF) and up-regulation of four other coagulation genes (F5, F10, PROS1 and F2R)." (PMID 26445145, 2015).
F2R also shares sentences with these, for which no sentence is quoted: Sepsis (9 papers); Stroke (9); acute coronary syndrome (7); colon carcinoma (4); endothelial dysfunction (4); brain hemorrhage (3); colorectal cancer (3); coronary artery disease (3); Diabetes (3); metastatic melanoma (3); pulmonary fibrosis (3); Arthritis (2); Cerebral ischemia (2); diabetic nephropathy (2); gastritis (2); glioblastoma (2); heart failure (2); hepatocellular carcinoma (2); injury (2); intracerebral hemorrhage (2); ischemic stroke (2); neurodegenerative disease (2); Obesity (2); preeclampsia (2); psoriatic arthritis (2); thrombosis (2); acute lymphoblastic leukemia (1); aortic aneurysm (1); aortic stenosis (1); arterial hypertension (1).
A further 59 diseases each share a sentence with F2R in 1 paper.